LYST (lysosomal trafficking regulator)
Diseases named in the same sentence as LYST in open-access papers (continued):
Sharing a sentence is not in itself a finding about the gene and the disease.
oculocutaneous albinism (7 papers, 2013 to 2025). Oculocutaneous albinism (OCA) describes a group of inherited disorders of melanin biosynthesis characterized by a generalized reduction in pigmentation of hair, skin and eyes and variable ocular findings including nystagmus, reduced visual acuity and photophobia. "Mutations in RAB27A, LYST, and AP3B1 give rise to FHL associated with oculocutaneous albinism, and patients with FHL are usually only screened for mutations in these genes when albinism is observed." (PMID 25312756, 2015). "Lysosomal trafficking regulator (LYST) gene mutations underlie CHS disease, the main symptoms of which are partial oculocutaneous albinism, immune dysfunction, neurodegeneration, prolonged bleeding, and a risk for hemophagocytic lymphohistiocytosis development." (PMID 38675481, 2024). "Chediak‐Higashi syndrome (CHS), due to a defect in the LYST gene, is characterized, like HPS, by oculocutaneous albinism and a bleeding diathesis due to platelet storage pool deficiency." (PMID 40387003, 2025). "This evidence establishes a molecular explanation for commonly reported oculocutaneous albinism of CHS patients and the LYST-dependent melanosome/lysosome events required for normal skin, hair, and eye pigment distribution." (PMID 38774881, 2024).
albinism (6 papers, 2015 to 2022). A congenital disorder characterized by partial or complete absence of melanin pigment in the eyes, hair, or skin. "HPS and CHS are syndromic albinism caused by mutations in genes such as HPS1–10 and CHS1, respectively, which encode proteins HPS1, adaptor protein (AP-3) β3A, HPS3, HPS4, HPS5, HPS6, Dysbindin, BLOS3, Pallidin, AP-3 δ, and LYST." (PMID 30104399, 2018).
hemophagocytic lymphohistiocytosis (6 papers, 2020 to 2024). "Others include known genetic causes of hemophagocytic lymphohistiocytosis (HLH) such as defects in the genes PRF1, UNC13D, STX11, STXBP2, LYST, and RAB27A." (PMID 38624552, 2020).
multiple myeloma (4 papers, 2014 to 2024). "LYST is a lysosomal trafficking regulator that promotes proliferation and inhibits apoptosis in multiple myeloma, and also harbors driver mutations for rare bone tumors." (PMID 33396385, 2020). "Silencing LYST expression using anti-LYST siRNA inhibited proliferation and induced apoptosis in multiple myeloma cells." (PMID 38774881, 2024). "LYST also localized within copy number aberration regions in patients with multiple myeloma." (PMID 38774881, 2024). "LYST gene silencing may inhibit cell proliferation and induce apoptosis in myeloma cells." (PMID 29854292, 2018). "LYST was recently established as a gene of interest in patients with acute myeloid leukemia (AML), colorectal cancer, epithelial ovarian cancer, multiple myeloma, pulmonary carcinosarcoma, and sporadic chordoma." (PMID 38774881, 2024). "Chromosomal segments containing genes such as LYST, CLK1, ACSL1 and NFKB1A were amplified in more than 40% of myeloma patients in this study." (PMID 24690091, 2014).
Familial hemophagocytic lymphohistiocytosis (3 papers, 2013 to 2024). Familial Hemophagocytic lymphohistiocytosis (FHL) is a rare primary immunodeficiency characterized by a macrophage activation syndrome (see this term) with an onset usually occurring within a few months or less common several years after birth. "Additionally, and in agreement with a previous report, we also detected rare heterozygous mutations in some genes, including AP3B1, PRF1, LYST and DOCK8, that are associated with familial hemophagocytic lymphohistiocytosis in patients with MIS-C." (PMID 36282598, 2023).
exfoliation syndrome (2 papers, 2010). An autosomal dominant disorder caused by mutations in the LOXL1 gene, encoding lysyl oxidase homolog 1. "Mutations in the LYST gene are involved in Chediak-Higashi and exfoliation syndromes characterized by iris pigmentation dispersion, transillumination and other defects." (PMID 20463881, 2010). "Mice studies showed that LYST mutations reproduced the iris defects of human exfoliation syndrome." (PMID 20463881, 2010). "Furthermore, LYST, and other genes influencing oxidative stress, are suggested as candidates worthy of consideration for contributing to hereditary forms of exfoliation syndrome which is likely to also be strongly influenced by genetic modifiers." (PMID 20617205, 2010).
Primary hemophagocytic lymphohistiocytosis (2 papers, 2022 to 2024). "Rare heterozygous missense variants in genes responsible for primary hemophagocytic lymphohistiocytosis (LYST, STXBP2, PRF1, UNC13D, AP3B1, and DOCK8) were found in patients with MIS-C." (PMID 38397896, 2024). "Thirty-nine children were diagnosed with MIS-C, and 25.4% of the 39 MIS-C patients harbored rare heterozygous missense mutations either in primary hemophagocytic lymphohistiocytosis (pHLH) genes (LYST, STXBP2, PRF1, UNC13D, AP3B1) or the HLH-associated gene DOCK8 (four variants)." (PMID 35336791, 2022).
rheumatoid arthritis (2 papers, 2017 to 2024). A chronic, systemic autoimmune disorder characterized by inflammation in the synovial membranes and articular surfaces. "LYST encodes a lysosomal trafficking regulator whilst ATG4D is a cysteine peptidase involved in autophagy and this locus is associated with multiple sclerosis, psoriasis, and rheumatoid arthritis." (PMID 29059182, 2017).
viral infection (2 papers, 2024). "Another non-synonymous variant of unknown significance in the LYST gene (p.A1683V), which is autosomal recessive monogenic gene for systemic inflammatory syndrome, and a potential combination of heterozygous mutations in LYST in children with viral infection can lead to MIS-C." (PMID 39844836, 2024).
atopic dermatitis (1 paper, 2021). "We present a 6-year-old male patient with markedly elevated IgE and severe atopic dermatitis presenting with staphylococcal bacteremia found to have a heterozygous variant in FLG (p.S3247X) and multiple variants of unknown significance in BCL11B, ZAP70, LYST, and PTPRC." (PMID 34603803, 2021).
Epstein-Barr virus infection (1 paper, 2019). An infection that is caused by Epstein-Barr virus. "This is the first case report in which adult HLH was associated with novel digenic mutations of STXBP2 and LYST combined with Epstein-Barr virus infection." (PMID 30782130, 2019).
glaucoma (1 paper, 2021). Increased pressure in the eyeball due to obstruction of the outflow of aqueous humor. "Future studies of these rare variants have the potential to provide more general insights about TYRP1 and LYST protein function and biological pathways that are important in pigmentation, PDS, and the development of glaucoma." (PMID 34174832, 2021).
H1N1 influenza (1 paper, 2022). "A prior respiratory pandemic pathogen, H1N1 influenza, is one such example, where heterozygous missense mutations in primary HLH genes (PRF1, LYST) were identified in 36% of fatal cases." (PMID 35336791, 2022).
hereditary spastic paraplegia (1 paper, 2014). Hereditary spastic paraplegias (HSP) comprise a genetically and clinically heterogeneous group of neurodegenerative disorders characterized by progressive spasticity and hyperreflexia of the lower limbs. "A rare neurologic disorder, named hereditary spastic paraplegia (HSP) and characterized by leg spasticity, weakness, hyperreflexia, and additional neurological symptoms, was recently reported in two adult siblings with HSP and homozygous LYST pathogenic mutation." (PMID 24795715, 2014).
lymphoma (1 paper, 2025). A malignant (clonal) proliferation of B- lymphocytes or T- lymphocytes which involves the lymph nodes, bone marrow and/or extranodal sites. "The remaining 8 (29.6%) patients, including 6 from the same family with NHEJ1 mutations and 2 with LYST mutations, developed secondary MDS (sMDS)/AML or lymphoma, with a family history suggestive of FHM." (PMID 40047910, 2025).
medulloblastoma (1 paper, 2025). A malignant, invasive embryonal neoplasm arising from the cerebellum. "Our patient had additional mutations at POLE, LYST, KMT2D, and TERT, all of which have been shown to significantly reduce overall survival in medulloblastoma." (PMID 40958970, 2025).
Obesity (1 paper, 2025). Accumulation of substantial excess body fat. "Although the overall statistical significance was modest, two loci—LYST (rs184772418) and HDAC9 (rs13247375)—demonstrated statistically significant interaction effects on HOMA-IR levels within obesity subgroups, based on an interaction p-value threshold <0.05." (PMID 40699860, 2025).
pancreatic cancer (1 paper, 2026).
periodontitis (1 paper, 2025). An acute or chronic inflammatory process that affects the tissues that surround and support the teeth. "Moreover, there are a few dental clinics in the United States that offer genetic testing for aggressive periodontitis (AP) and Sjogren’s syndrome by testing mutations in Cathepsin C (CTSC), LYST, COL5A1, FcyIIB, and FPRI for AP." (PMID 40136761, 2025).
primary immunodeficiencies (1 paper, 2018). "Furthermore, several heterozygous variants were identified in genes associated with known primary immunodeficiencies that are inherited in an autosomal recessive manner, such as LYST, LRBA, RAG1, EXTL3, and STX11 (Group 4)." (PMID 30723478, 2018).
sarcoidosis (1 paper, 2024). Sarcoidosis is a multisystemic disorder of unknown cause characterized by the formation of immune granulomas in involved organs. "Our integrated model revealed several novel genes and miRNAs between sarcoidosis and controls, including LYST, RGS14, SLFN12L, and hsa-miR-199b-5p." (PMID 39080656, 2024). "Specifically, LYST, a regulator of endosome/lysosome trafficking, can regulate TLR3 and TLR4 mediated pathways, genes involved in the innate immune system which have been implicated in sarcoidosis." (PMID 39080656, 2024). "Novel immune related genes and miRNAs including LYST, RGS14, SLFN12L, and hsa-miR-199b-5p, distinguished sarcoidosis from controls." (PMID 39080656, 2024).
spinal chordoma (1 paper, 2021). A slow-growing malignant bone tumor arising from the remnants of the notochord and occurring in the spine. "Our analysis of 32 spinal chordomas identified alterations in LYST, PTEN, CDC27, and ARID1A at similar frequencies compared with their spinal chordoma cohort." (PMID 33543146, 2021).
infection (18 papers, 2011 to 2025). The state of being infected such as from the introduction of a foreign agent such as serum, vaccine, antigenic substance or organism. "The significantly downregulated genes (NEAT1, TPM3, ZNHBA, CKLF, and OSBPL8) and the upregulated genes (ITMZC, IFNG, CD69, DNAJB9, and LYST) in NCAM1+FCGR3A+dNK cells after infection were also analyzed." (PMID 38730500, 2024).
genetic disorder (5 papers, 2019 to 2025). "Included among the genetic disorders associated with the occurrence of HLH, mutations affecting lysosomal trafficking regulator (LYST) affect biogenesis of cytolytic granules, whereas AP3 mutations affect lytic granule polarization." (PMID 35269412, 2022). "The corresponding gene LYST can potentially result in genetic diseases." (PMID 31332212, 2019).
cancer (4 papers, 2017 to 2024). A tumor composed of atypical neoplastic, often pleomorphic cells that invade other tissues. "The association of LYST mutations with various forms of cancer is a chance discovery stemming from next generation sequencing analysis." (PMID 38774881, 2024). "Over the past decade alone, LYST has been linked to human health outside of CHS through connections to cancer and wound healing." (PMID 38774881, 2024). "Currently, studies are correlative but not mechanistic; authors appear to be divided on whether the connection of LYST to cancer is a spurious correlation or if LYST mutations truly drive cancer progression." (PMID 38774881, 2024). "Currently, the trend seems to be that downregulation or truncation of LYST protein leads to cancer progression." (PMID 38774881, 2024). "LYST mutations appear to be associated with certain cancer types, yet its potential role in cancer is not yet understood." (PMID 38774881, 2024). "The gene with the highest accumulation of windows is LYST (14 windows), a lysosomal trafficking regulator whose relationship with cancer is not evident." (PMID 30486775, 2018).
tumor (4 papers, 2017 to 2025). "In the discovery cohort, five tumours (14%) harboured a single LYST mutation each." (PMID 29026114, 2017). "This would suggest that LYST is not a classic two-hit tumour suppressor gene." (PMID 29026114, 2017).
neurodegenerative disease (1 paper, 2025). A disorder of the central nervous system characterized by gradual and progressive loss of neural tissue and neurologic function. "Moreover, altered expression of lysosomal trafficking regulator (Lyst) and spastizin (Zfyve26) leads to neuronal degeneration and neurodegenerative diseases." (PMID 41002437, 2025).
neurological disease (1 paper, 2025). "While LYST expression in fibroblasts may predict non-neurological disease severity, neurologic complications appear to be genotype-independent." (PMID 40704228, 2025).
LYST also shares sentences with these, for which no sentence is quoted: fungal infection (4 papers); bacterial infection (3); lysosomal storage disorder (3); Cognitive impairment (2); cyst (2); Hermansky-Pudlak syndrome (2); malignant melanoma (2); acute myeloid leukemia (1); Arrhythmogenic right ventricular dysplasia (1); asthma (1); atherosclerosis (1); autoimmune disease (1); Autoimmunity (1); bacteremia (1); Birk-Barel syndrome (1); bleeding disorder (1); bone marrow failure syndrome (1); bone tumors (1); breast carcinoma (1); cerebellar ataxia (1); Cohen syndrome (1); contact dermatitis (1); Crohn disease (1); Danon disease (1); deafness (1); Escobar syndrome (1); Griscelli syndrome (1); hematologic disorder (1); Hepatosplenomegaly (1); hyperferritinemia (1).
A further 29 diseases each share a sentence with LYST in 1 paper.